HSPA4 (heat shock protein family A (Hsp70) member 4)
Diseases named in the same sentence as HSPA4 in open-access papers (continued):
Sharing a sentence is not in itself a finding about the gene and the disease.
prostate carcinoma (3 papers, 2019 to 2025). A carcinoma that arises from epithelial cells of the prostate gland. "HSPA4, a member of the heat shock protein A family, has been predominantly studied in cancer contexts, including breast, lung, and prostate cancer." (PMID 40076916, 2025).
breast tumor (2 papers, 2024 to 2025). "Then, in contrast to normal breast tissue, breast tumor tissue had considerably lower MAOB expression levels and higher levels of CYCS, XBP1, HSPA4, APEX1, and SERP1." (PMID 41367017, 2025).
cardiac hypertrophy (2 papers, 2021 to 2025). "Deletion of HSPA4 accelerates cardiac hypertrophy and fibrosis." (PMID 35115946, 2021).
gastric ulcer (2 papers, 2016 to 2023). An ulcerated lesion in the mucosal surface of the stomach. "Heat shock protein family A (Hsp70) member 4 (HSPA4) is associated with gastric ulcer." (PMID 36624383, 2023).
heart failure (2 papers, 2020 to 2025). Inability of the heart to pump blood at an adequate rate to meet tissue metabolic requirements. "Furthermore, through literature research, we found that some MYC target genes were previously reported involving the development of heart failure, including STAT3, PRMT1, PRKCH and HSPA4." (PMID 32460775, 2020).
osteosarcoma (2 papers, 2023 to 2024). A usually aggressive malignant bone-forming mesenchymal neoplasm, predominantly affecting adolescents and young adults. "The maximum and median fractions of mutated reads in tumors were 0.59 and 0.35, respectively, indicating that mutations were monoallelic, with the exception of a missense HSPA4 mutation in one osteosarcoma specimen (0.97)." (PMID 38318504, 2023).
ameloblastoma (1 paper, 2021). The most common odontogenic tumor, arising from the epithelial component of the embryonic tooth and usually affecting the molar-ramus region of the mandible or maxilla. "Our findings of recurrent somatic mutation on HSPA4 suggest that its proto oncogene-like function may play a role in the pathology of Ameloblastoma." (PMID 33395399, 2021). "Key words:Ameloblastoma, whole exome sequencing, somatic mutation, BRAF, HSPA4, two-hit theory." (PMID 33395399, 2021).
cataract (1 paper, 2024). Partial or complete opacity of the crystalline lens of one or both eyes that decreases visual acuity and eventually results in blindness. "HspA4 levels were significantly lower in posterior subcapsular cataracts compared to post-traumatic, postpartum, or prenatal cataracts." (PMID 38999417, 2024). "In prenatal cataracts, HspA4 expression was significantly higher than in secondary and infectious cataracts." (PMID 38999417, 2024).
dwarfism (1 paper, 2022). "In accordance with stunted growth, Hspa4-KO mice also exhibited generalized dwarfism affecting all organs tested." (PMID 35568953, 2022).
endometrial cancer (1 paper, 2024). Primary or metastatic malignant neoplasm involving the endometrium (mucous membrane that lines the endometrial cavity). "Remarkably, within endometrial cancer samples, we discerned a conspicuous mutation frequency in HSPA4 exceeding 6%." (PMID 38305786, 2024).
epilepsy (1 paper, 2023). A brain disorder characterized by episodes of abnormally increased neuronal discharge resulting in transient episodes of sensory or motor neurological dysfunction, or psychic dysfunction. "Interestingly, it has also been reported that HSPA4, during the latency phase following status epilepticus, shows a significant upregulation in subregions of the temporal lobe crucial for the development of TLE and in a pilocarpine model of this type of epilepsy." (PMID 36980356, 2023).
Hyperglycemia (1 paper, 2020). An increased concentration of glucose in the blood. "Moreover, the result revealed that the HSPA4 heat shock 70 kDa protein 4 genes responded to the activation of oxidative stress, protein-folding, and secretion demands that can be found in hyperglycemia." (PMID 32587797, 2020).
large cell neuroendocrine carcinoma of the lung (1 paper, 2025). "The NSCLC with PIAS1-RASGRF1 was a squamous cell carcinoma, while HSPA4-RASGRF2 was identified in a large cell neuroendocrine carcinoma of the lung." (PMID 40615519, 2025).
melanoma (1 paper, 2024). A malignant, usually aggressive tumor composed of atypical, neoplastic melanocytes. "It upregulates DAMPs (HMGB1, HSPA4, and HSP90AA1) in melanoma cells, for example." (PMID 39759512, 2024).
multiple sclerosis (1 paper, 2022). A progressive autoimmune disorder affecting the central nervous system resulting in demyelination. "Furthermore, HSPA4 from the heat shock protein family (70 kDa) is associated with demyelination in the peripheral nervous system and multiple sclerosis incidence." (PMID 35676653, 2022). "Moreover, we found that the relative expression of the Hspa4 was significantly decreased in the Multiple sclerosis rats model compared with the Control group." (PMID 35676653, 2022). "The maximum reduction of Dnajb1/Dnajb2/Foxp1/Tnfsf14 network was observed when Multiple sclerosis rats were treated with exercise training and 100 mg/kg Royal jelly (ET-RJ100), but the relative expression of the Hspa4 significantly increased." (PMID 35676653, 2022). "The maximum reduction of the Dnajb1/Dnajb2/Foxp1/Tnfsf14 network was observed when Multiple sclerosis rats were treated with exercise training and 100 mg/kg Royal jelly (ET-RJ100), but the relative expression of the Hspa4 significantly increased." (PMID 35676653, 2022).
non-small cell lung carcinoma (1 paper, 2024). A group of at least three distinct histological types of lung cancer, including non-small cell squamous cell carcinoma, adenocarcinoma, and large cell carcinoma. "In non-small cell lung cancer, HSPA4 has shown its potential as an oncogene." (PMID 38305786, 2024).
Obesity (1 paper, 2025). Accumulation of substantial excess body fat. "Nevertheless, research examining the relationship between HSPA4 and obesity is limited." (PMID 40076916, 2025).
pheochromocytoma (1 paper, 2019). "Notably, associations with AKT1 and HSPA4 are not impaired in pheochromocytoma." (PMID 30943211, 2019).
psoriasis (1 paper, 2024). An autoimmune condition characterized by red, well-delineated plaques with silvery scales that are usually on the extensor surfaces and scalp. "Subsequently, WGCNA showed the hub genes (e.g., S100A12, CYCS, NOD2, STAT1, HSPA4, AIM2, MAPK7), which were significantly associated with clinical phenotype, PANoptosis signature, and identified immune response in psoriasis." (PMID 38125299, 2024).
renal cell carcinoma (1 paper, 2023). "This study aimed to investigate the HSP70 (HSPA4) gene expression signature in patients with renal cell carcinoma (RCC) in correlation to cancer subtype, stage, grade, and recurrence, combining both clinicopathological and in silico analysis approaches." (PMID 36833281, 2023).
spastic diplegia (1 paper, 2015). A type of cerebral palsy characterized by spasticity and hypertonia of the lower extremities bilaterally, particularly the legs, hips, and pelvis; this is the most common (70%) form of cerebral palsy. "Case 4-10C with spastic diplegia (GMFCS I) had a de novo 48 kb duplication affecting HSPA4 (mentioned previously), but no other risk factors for CP." (PMID 26236009, 2015).
teratoma (1 paper, 2025). A non-seminomatous germ cell tumor characterized by the presence of various tissues which correspond to the different germinal layers (endoderm, mesoderm, and ectoderm). "Similarly, the miRNA regulatory network associated with teratoma hub genes demonstrates distinct miRNA clusters targeting essential oncogenic regulators such as CDK1, HSP90AA1, HSPA4, TRIM28, and TOP2A." (PMID 40869426, 2025).
type 2 diabetes mellitus (1 paper, 2021). A type of diabetes mellitus that is characterized by insulin resistance or desensitization and increased blood glucose levels. "Previous work has shown elevation of HSPA4 to occur in tandem with length of time since diagnosis in type 2 diabetes mellitus (T2DM)." (PMID 34685777, 2021).
viral infections (1 paper, 2024). "The research indicates that HSPA4 could potentially serve as a target for developing resistance against viral infections." (PMID 39599898, 2024). "However, the role of HSPA4 in virus infection is rarely reported." (PMID 39599898, 2024).
tumor (43 papers, 2010 to 2025). "To comprehensively elucidate the genetic alterations of HSPA4 in various cancers, we employed the cBioPortal tool, leveraging the TCGA database, to meticulously investigate its genetic mutations across numerous tumor samples." (PMID 38305786, 2024). "Lastly, the interaction of HSPA4 with immune cells is linked to the tumor microenvironment (TME) and immunotherapy." (PMID 38305786, 2024). "Upon rigorous exploration of genetic variations in the HSPA4 gene across diverse cancers, we identified significant mutations of HSPA4 in several tumor types." (PMID 38305786, 2024). "Firstly, we identify that HSPA4 is upregulated in GC tumor tissues and the upregulation of HSPA4 is positively associated with poor survival in patients with GC." (PMID 38589927, 2024). "HSPA4 is implicated in the pathogenesis of various diseases, particularly cancer, and its expression level is closely linked to tumor invasion and metastasis." (PMID 39599898, 2024). "Among the identified protein biomarkers of PAS, we selected HSPA4 for further functional assays since it was implied to be associated with tumor metastasis, a biological activity for which angiogenesis is usually enhanced." (PMID 35628491, 2022). "Recent research reported that HSPA4 is a tumor membrane antigen that can promote tumor metastasis by activating the NF-κB pathway in tumor cells once ligated with the pathogenic anti-HSPA4 IgG." (PMID 33816550, 2021). "Here, B cell-derived pathogenic antibodies target the tumor antigen HSPA4 and promote the formation of the premetastatic niche in tumor-draining lymph nodes." (PMID 31963450, 2020). "Histone acetylation causes HSPA4 upregulation in GC tumor tissues." (PMID 38589927, 2024). "Pathogenic IgG targeting glycosylated membrane HSPA4 selectively promotes lymph node metastasis and activates the downstream Src/NF-κB in ITGB5 and tumor cells for CXCR4/SDF1α axis-mediated metastasis." (PMID 41357192, 2025). "Cell lines were also detected and HSPA4 was significantly increased in GC cells compared with pooled non-tumor tissues." (PMID 38589927, 2024). "Harnessing the computational power of the EPIC, MCPCOUNTER, XCELL, and TIDE algorithms, we embarked on an exhaustive assessment of the dynamic relationship between CAFs infiltration and HSPA4 gene expression across diverse tumor types in the TCGA database." (PMID 38305786, 2024). "Taken together, these results suggest that the upregulation of HSPA4/ALKBH5/CD58 signaling axis in GC tumor cells negatively regulates the infiltration of CD8+ T cells in GC tumor mass." (PMID 38589927, 2024). "The results exhibited that HSPA4 overexpression facilitated tumor growth compared with the control cells, as reflected by tumor size and weight (P < 0.05)." (PMID 38589927, 2024). "Western blotting results indicated that HSPA4 protein level was significantly increased in 7/12 GC tissues compared with non-tumor tissues." (PMID 38589927, 2024). "A mouse model of breast cancer demonstrated that primary tumors induced an aberrant immune response, leading to the production of IgG antibodies targeting glycosylated membrane protein HSPA4 and ultimately promoting tumor progression." (PMID 39519376, 2024). "Correlation analysis results demonstrated that ALKBH5 correlated positively with HSPA4 while negatively with CD58 in GC tumor tissues." (PMID 38589927, 2024). "Although HSPA4 has been observed to exhibit elevated expression levels in tumor tissues compared to normal tissues, its potential utility in cancer diagnosis and prognosis remains to be elucidated through further in-depth studies." (PMID 38305786, 2024). "Intriguingly, in our analysis, HSPA4 demonstrated correlations with these survival indices across multiple tumor types, typically exhibiting consistent trends in most cases." (PMID 38305786, 2024). "In this study, we illustrate that HSPA4 is upregulated in GC tumor tissues and mediates immune escape of tumor cells." (PMID 38589927, 2024).
tumor (continued). "The clinical significance of HSPA4 upregulation was analyzed by multiplex fluorescent immunohistochemistry staining in GC tumor tissues." (PMID 38589927, 2024). "Our data revealed that, relative to their normal tissue counterparts, there was a pronounced increase in the methylation levels of the HSPA4 promoter region in various tumor types." (PMID 38305786, 2024). "A particular emphasis was placed on the correlation of HSPA4 with functional states in specific tumor types." (PMID 38305786, 2024). "Inhibition of the HSPA4 gene substantially diminishes the invasive and metastatic capabilities of tumor cells." (PMID 38305786, 2024). "HSPA4 overexpression greatly increased the tumor weight and volume, while 4-PBA treatment reduced them compared with the control group." (PMID 35442158, 2022). "Animal experiments showed similar results that 4-PBA repressed tumor growth and inactivated the two pathways, while HSPA4 overexpression reversed the effects of 4-PBA." (PMID 35442158, 2022). "We will provide clinical data to validate key conclusions like HSPA4 expression pattern or ER stress status in BC tumor tissues in the future." (PMID 35442158, 2022). "Immunohistochemical staining of clinical HCC samples also confirmed that the level of HSPA4 in tumor tissues was higher than that in adjacent normal liver tissues." (PMID 34754620, 2021). "To further explore the role of HSPA4 in the tumor immune micro-environment, we identified the correlation between HSPA4 expression and biomarkers of immune cells in HCC using the TIMER database." (PMID 34754620, 2021). "The high HSPA4 expression was associated with vascular invasion, while the high HSPA14 expression with the higher T stage of the tumor." (PMID 34059060, 2021). "From the ROC curve of diagnosis, HSPA4 expression showed an ability to accurately identify tumor from normal tissue (AUC = 0.957)." (PMID 34754620, 2021). "HSPA4 expression showed a good ability to distinguish tumor from normal tissue, and to predict 1-, 3-, and 5-year survival rates, indicating that it can be used as a potential valuable diagnostic and prognostic biomarker for HCC." (PMID 34754620, 2021). "Other studies showed that HSPA9 and HSPA4 influence the biological behavior of tumor cells to promote cancer progression." (PMID 34712697, 2021). "Among the signature genes we researched, HSPA4, FABP6, S100A10, CACYBP, SHC1 and HDAC1 were associated with a higher tumor grade, CACYBP was linked with a higher clinical stage as well as T stage." (PMID 32191631, 2020). "As described in the literature, HSPA4 is a tumor membrane antigen having a role in tumor metastasis through activating the NF-κB pathway." (PMID 32793473, 2020). "Recent studies have indicated that knockdown of HSPA4 can significantly reduce the migration, invasion, and transformation activities of tumor cells." (PMID 32523426, 2020). "HSPA4 is highly expressed in malignant tumor cells and is involved in tumor development and chemotherapy resistance, presumably due to its ability to inhibit tumor cell apoptosis." (PMID 32523426, 2020). "HSPA4 may impact tumor development through various mechanisms, including the modulation of cyclin and apoptosis-related proteins as well as the activation of the Akt signaling pathway." (PMID 39599898, 2024). "These insights further emphasize the central position of HSPA4 in tumor biology." (PMID 38305786, 2024). "Because the expression of HSPA4 was significantly correlated with the tumor proliferation signature in TCGA GC dataset, we established stable HSPA4-overexpressing GC cells (MKN45-HSPA4 and HGC27-HSPA4) and HSPA4 knockdown cells (AGS-sh) to explore the function of HSPA4 in GC cells." (PMID 38589927, 2024). "CD8+ T cells infiltration is also decreased in tumor tissues with HSPA4 upregulation." (PMID 38589927, 2024). "In addition, ALKBH5 is upregulated and CD58 is downregulated in tumor tissues with HSPA4 upregulation." (PMID 38589927, 2024).